OR10P1 (olfactory receptor family 10 subfamily P member 1)
Description:
Odorant receptor.
Synonyms: OR10P1P; OR10P2P; OR10P3P; OST701; OR12-7
Tractability: Small molecule: it belongs to a druggable protein family. Antibody: its Gene Ontology location is reachable by antibodies, with high confidence; UniProt places it where antibodies can reach, with medium confidence; UniProt predicts a signal peptide or a membrane-spanning region; the Human Protein Atlas places it where antibodies can reach.
Gene: Protein-coding gene on chromosome 12 (55,636,892 to 55,637,833, forward strand). Ensembl gene ENSG00000175398.
Subcellular location: Cell membrane
Subcellular location (Human Protein Atlas): Plasma membrane
Pathways (Reactome):
Sensory Perception: Expression and translocation of olfactory receptors
Gene Ontology:
Molecular function: olfactory receptor activity; G protein-coupled receptor activity
Biological process: detection of chemical stimulus involved in sensory perception of smell; G protein-coupled receptor signaling pathway
Cellular component: plasma membrane; membrane
Genetic constraint (gnomAD): Loss-of-function variants: 1 observed, 0.28 expected, observed/expected ratio (o/e) 3.51. That is too few expected variants to judge how well the gene tolerates losing a copy. Missense variants: 424 observed, 425.21 expected, observed/expected ratio (o/e) 1, 90% interval 0.92 to 1.08. Synonymous variants: 178 observed, 178.45 expected, observed/expected ratio (o/e) 1, 90% interval 0.88 to 1.13.
Homologues: Orthologues: macaque OR10P1 (96% identical), mouse Or10p1 (84% identical), pig OR10P1 (84% identical), rabbit OR10P1 (84% identical), rat Or10p1 (80% identical), guinea pig OR10P1 (79% identical). Paralogues in human: OR10C1 (49% identical), OR10A4 (49% identical), OR10A5 (48% identical), OR10A7 (47% identical), OR10A2 (46% identical), OR10AG1 (46% identical), OR10A3 (45% identical), OR5V1 (45% identical), OR13C3 (45% identical), OR2D2 (45% identical), OR10A6 (44% identical), OR10H1 (43% identical), and 80 more.
Diseases named in the same sentence as OR10P1 in open-access papers:
OR10P1 is named in the same sentence as 1 disease in open-access papers, as found by Europe PMC text mining. Sharing a sentence is not in itself a finding about the gene and the disease.
OR10P1 shares sentences with these, for which no sentence is quoted: pancreatic cancer (2 papers).